APOE (apolipoprotein E)
Diseases named in the same sentence as APOE in open-access papers (continued):
Sharing a sentence is not in itself a finding about the gene and the disease.
Alzheimer disease (continued). "ApoE is the probably the most important and acknowledged genetic risk factor for Alzheimer’s disease and even for some other neurological disorders." (PMID 26175714, 2015). "The apolipoprotein E-ε4 allele is a well-known genetic risk factor for late-onset Alzheimer’s disease, which also impacts the cognitive functions and brain network connectivity in healthy middle-aged adults without dementia." (PMID 26053677, 2015). "Apolipoprotein E (APOE) ε4 is a major genetic risk factor for Alzheimer’s disease (AD), yet the mechanisms by which APOE-ε4 influences early-life brain function, and hence, in turn, risk for later-life AD, are poorly understood." (PMID 26552581, 2015). "There is a strong association between the presence of apolipoprotein E ε4 (APOE-ε4) and increased risk of Alzheimer's disease (AD)." (PMID 25630472, 2015). "Possession of the ε4 allele of the Apolipoprotein E (APOE) gene is associated with an increased risk of Alzheimer’s disease." (PMID 26287823, 2015). "In course of this public release, on the basis of Dr. Watson’s request, all the gene information about apolipoprotein E (ApoE) had been removed due to concerns regarding a shown association between this gene and late-onset Alzheimer’s disease (LOAD)." (PMID 26085313, 2015). "APOE genotype/expression has been linked to human neurocognitive and neuroinflammatory disorders (e.g., Alzheimer’s disease, Parkinson’s disease multiple sclerosis and HIV disease progression)." (PMID 25822971, 2015). "While our human data do not reveal sex-specific association of APOE genotypes and MS severity, the association of APOE genotypes with Alzheimer’s disease (AD) has been described to be modulated by sex and ethnicity." (PMID 26669675, 2015). "APOE was initially investigated because its ɛ4 allele was known to increase the risk of Alzheimer’s disease and coronary artery disease, while FOXO3 was tested because its homologs influence lifespan in C. elegans, Drosophila and mice." (PMID 26677855, 2015). "This figure does not include sporadic neurodegenerative diseases with a complex genetic architecture involving many different genetic loci, such as APOE, which has a moderately strong influence on the risk of developing Alzheimer disease." (PMID 26341866, 2015). "In parallel, two APOE polymorphisms, i.e., rs429358 (ε4, Cys130Arg) and rs7412 (ε2, Arg176Cys), which represent established risk variants in Alzheimer’s disease, have been assessed extensively for their role in MS." (PMID 26669675, 2015). "We have previously shown that possessing an e4 allele of the apolipoprotein E (APOE) gene correlates with increased cognitive decline in older age and it confers a higher risk of developing Alzheimer’s disease." (PMID 26335101, 2015). "The accumulation of amyloid in neurons also depended on the apolipoprotein E genotype, which is a known genetic risk factor for Alzheimer’s disease." (PMID 26063233, 2015). "The APOE locus is also strongly associated with neurological disease (particularly Alzheimer’s disease), cardiac, metabolic, and vascular diseases, plasma C-reactive protein levels, and, in a recent study, nonpathological cognitive aging." (PMID 26077337, 2015). "The presence of one or two copies of the epsilon 4 allele (ε4) in the apolipoprotein E (APOE) gene is one commonly accepted genetic characteristic believed to increase the risk of development of dementia due to Alzheimer’s disease (AD)." (PMID 26537709, 2015). "The apolipoprotein E ε4 (APOE-ε4) allele is a strong genetic risk factor for Alzheimer's disease (AD)." (PMID 25630472, 2015). "Apolipoprotein E ε4 (APOE ε4) is a well-known risk factor affecting the likelihood and age of onset of Alzheimer’s disease (AD), with a dose dependence characteristic (i. e., two alleles are associated with an increased risk compared to one)." (PMID 25738563, 2015).
Alzheimer disease (continued). "Most consistently, effects of the APOE polymorphism on cognition and etiopathology have been described for patients suffering from Alzheimer's disease, but it's effects on cognitive functions in healthy older adults has also been reported." (PMID 26528177, 2015). "The APOE effect on Alzheimer Disease (AD) risk is stronger in women than in men but its mechanisms have not been established." (PMID 26397226, 2015). "All of the common loci that have been linked to late onset Alzheimer’s disease (AD) other than APOE have small effect sizes and a large portion of the predicted heritability for AD remains unidentified." (PMID 26625115, 2015). "The apolipoprotein E-ε4 (APOE-ε4) allele is a well-known genetic risk factor for late-onset Alzheimer’s disease (AD), causing symptoms after age 65 years." (PMID 26053677, 2015). "ApoE function is known to be down-regulated in AD patients, and carrying the ApoE4 allele increases risk of Alzheimer's disease." (PMID 26462180, 2015). "The genetic origin of the three common variants of the human apolipoprotein E (apoE) protein, known as E2, E3 and E4, has been related to a number of age-related diseases, including Alzheimer disease, as well as to healthy aging and longevity." (PMID 24924924, 2014). "Apolipoprotein E (APOE) ε genotype has previously been significantly associated with cognitive, brain imaging, and Alzheimer's disease-related phenotypes (e.g., age of onset)." (PMID 24508314, 2014). "This signaling involves physiological mediators of synaptic development, maintenance, repair, and remodeling, including APP, its derivative peptides, ApoE, and tau, and is modulated by all of the many disparate factors associated with Alzheimer's disease." (PMID 25324467, 2014). "Ethnic differences in genetic effects are well known: the meta-analysis of the effects of the APOE risk gene for Alzheimer’s disease shows a difference between European and Asian populations." (PMID 24399358, 2014). "Recent genome-wide association studies (GWAS) of late-onset Alzheimer’s disease (LOAD) have identified single nucleotide polymorphisms (SNPs) which show significant association at the well-known APOE locus and at nineteen additional loci." (PMID 24607147, 2014). "LRP2, whose ligand ApoE is known for the risk of Alzheimer’s disease, is expressed in brain and facilitates the clearance of the Aβ peptide, that is, the cause of Alzheimer’s disease." (PMID 24366390, 2014). "Currently, only the ε4 allele of apolipoprotein E (ApoE) is considered a risk factor for Late Onset Alzheimer Disease (LOAD)." (PMID 24586483, 2014). "The effects of the APOE genotype on the increased risk of Alzheimer's disease are likely to be mediated by the differential effects of apoE4 on amyloid-β accumulation in the brain." (PMID 25530658, 2014). "Apolipoprotein E (APOE) has previously been linked to Alzheimer's disease, where the ε4 allele is a risk factor and the ε2 allele is considered protective." (PMID 25299611, 2014). "Apolipoprotein E (ApoE) typing is considered important because of the association between ApoE and Alzheimer’s disease and familial dyslipidemia and is currently performed by genetic testing (APOE genotyping)." (PMID 24454848, 2014). "APOE has three allelic variants (APOE2, 3 and 4), and APOE4 carries the highest risk for Alzheimer’s dementia with APOE2 carrying the lowest." (PMID 25080285, 2014). "For example, the synonymous SNPs of corneodesmosin was associated with psoriasis onset, the synonymous SNPs of ApoE gene and low-density lipoprotein receptor-related protein 6 gene can increase the risk in developing Alzheimer's disease." (PMID 24596578, 2014). "The APOE e4 allele is also an established risk factor for dementia, in particular Alzheimer’s disease (AD), whereas as the APOE e2 allele is associated with a decreased risk for AD relative to the APOE e3 allele." (PMID 25325355, 2014).
Alzheimer disease (continued). "For example, a growing literature demonstrates that apolipoprotein e genotype, a known risk factor for adverse neurological outcomes like Alzheimer's disease, is also linked to lipid profiles in people with T2D including elevated levels of VLDL." (PMID 25057411, 2014). "This system allowed us to examine Aβ metabolism in vivo, and test the effects of both aging and APOE genotype, two of the strongest risk factors for Alzheimer’s disease." (PMID 25177293, 2014). "Although APOE ɛ4 is an established risk factor for late onset Alzheimer's disease and for worse cognitive ageing, this polymorphism accounts for only a small fraction of phenotypic variance." (PMID 25247594, 2014). "A possible exception is the Alzheimer’s disease (AD) risk gene, APOE: carriers of one or more risk-conferring alleles (APOE4) demonstrate accelerated gray matter loss with age." (PMID 24399358, 2014). "A recent study yielded first evidence that personality plays an important role in explaining the influence of a prominent APOE polymorphism on cognitive decline and Alzheimer’s disease (AD) in elderly humans." (PMID 24884737, 2014). "Possessing an apolipoprotein-E ε4 (APOE-ε4) allele increases the risk for developing the sporadic form of Alzheimer's disease (AD)." (PMID 24795624, 2014). "The ε4 allele of the gene that encodes apolipoprotein E (APOE4) is the greatest genetic risk factor for Alzheimer's disease (AD), while APOE2 reduces AD risk, compared to APOE3." (PMID 24328732, 2014). "The common variations of ApoE-ε2/3/4, defined by two common SNPs (rs7412 for ApoE ε2 and rs429358 for ApoE ε4), are the best established susceptibility gene for late-onset Alzheimer's disease (AD)." (PMID 24790992, 2014). "Having the apolipoprotein E4 (APOE-ε4) allele is the strongest genetic risk factor for the development of Alzheimer’s disease (AD)." (PMID 24948358, 2014). "The greatest genetic risk factor for late-onset Alzheimer's disease (AD) is the ε4 allele of Apolipoprotein E (ApoE)." (PMID 24456642, 2014). "Apolipoprotein E4 (Apo E4) is the major genetic risk factor in the causation of Alzheimer's disease (AD)." (PMID 24967370, 2014). "The ε4 allele of ApoE, a cholesterol transport protein, is the only known risk factor, other than aging, for late onset Alzheimer disease." (PMID 23585733, 2013). "We previously identified TMCC2 as a protein that interacted differentially with normal versus Alzheimer's disease-risk forms of both apolipoprotein E (apoE) and the amyloid protein precursor (APP)." (PMID 23409049, 2013). "In contrast, while several common alleles associated with late-onset Alzheimer's disease, including APOE, have been identified using association studies, the genetics of late-onset Alzheimer's disease are not fully understood." (PMID 23984328, 2013). "Bridging integrator 1 (Bin1), also downregulated by PCP in this study, has been associated with Alzheimer's disease together with apoE." (PMID 23738220, 2013). "As pointed out, the apolipoprotein E (APOE) malfunction still remains as the most important sequence variant that would be risk of Late-onset Alzheimer's disease." (PMID 23662159, 2013). "Individuals with a particular variant of a lipoprotein called ApoE (ApoE4) are also more likely to develop Alzheimer’s disease at a younger age than the rest of the population." (PMID 23986861, 2013). "Presence of one or two E4 alleles of Apolipoprotein E gene (ApoE) is widely known to be a strong risk factor for Alzheimer's disease (AD), but is also associated with other types of cognitive decline." (PMID 24386372, 2013).
Alzheimer disease (continued). "Our finding that even one APOE ε2 allele is protective against Aβ plaque deposition is consistent with previous reports associating this genotype with protection against Alzheimer’s disease." (PMID 24252240, 2013). "The present study investigated the extent to which the retina can be used as a model for studying the pathological effects of apolipoprotein E4 (apoE4), the most prevalent genetic risk factor for Alzheimer's disease (AD)." (PMID 23741431, 2013). "Polymorphic variation in the apolipoprotein E (apoE) gene is the major genetic susceptibility factor for late-onset Alzheimer's disease (AD) and likely contributes to neuropathology through various pathways." (PMID 23593485, 2013). "The apolipoprotein E4 (apoE4) genotype is a major risk factor for developing late-onset Alzheimer’s disease (AD)." (PMID 23845000, 2013). "Apolipoprotein E (ApoE) ε4 genotype is the strongest and most prevalent risk factor for late-onset Alzheimer’s disease (AD)." (PMID 23986861, 2013). "Although the risk factor for apolipoprotein E (apoE) polymorphism in Alzheimer's disease (AD) has been well described, the role that apoE plays in other neurodegenerative diseases, including Pick's disease, is not well established." (PMID 24312462, 2013). "Since more than a decade ApoE is known to be a strong risk factor for Alzheimer's disease (AD); however, molecular pathways mediating this risk are still unclear." (PMID 24386372, 2013). "Apolipoprotein-ε4 (APOE-ε4) is a major genetic risk factor for cognitive decline, Alzheimer's disease (AD) and early mortality." (PMID 23418430, 2013). "Carriers of the ApoE ε4 allele are at a greater risk for developing Alzheimer’s disease (AD) and those who do develop AD tend to have a much greater neuropathological disease burden." (PMID 23663404, 2013). "Further, a well-documented Alzheimer Disease risk-associated locus, APOE-ε4, has also been shown to be linked with risk for sporadic prion diseases, though delayed onset of inherited forms of prion diseases in humans with PrnpP102L is also observed." (PMID 23236467, 2012). "Several lines of evidence link apoE with late-onset Alzheimer's disease, the most common cause of dementia in the elderly." (PMID 23119149, 2012). "There are three allelic variants of the ApoE gene in humans (E2, E3, E4) with the E4 allele consistently being shown to confer a higher risk of developing both early and late onset Alzheimer's disease (AD)." (PMID 23152815, 2012). "Similar to the role of the ε4 allele APOE gene in the pathogenesis of Alzheimer's dementia, its association with elevated lipid levels and atherosclerosis have also been reported." (PMID 22577592, 2012). "The gene encoding apolipoprotein E (APOE) has been identified as playing an important role in the development of Alzheimer’s disease." (PMID 22815890, 2012). "Significant (P<0.05; two-sided) differences in gender, absence or presence of the APOE ε4 allele, age at death, Braak stage and the Consortium to Establish a Registry for Alzheimer's Disease (CERAD) score were observed between cases and controls." (PMID 23227193, 2012). "Apolipoprotein E (ApoE) is the strongest genetic risk factor for Alzheimer’s disease and has been implicated in the risk for other neurological disorders." (PMID 22675504, 2012). "This approach successfully identified the well-known apolipoprotein E (APOE) association with Alzheimer's disease, and the association of human leukocyte antigen (HLA) with many immune system disorders." (PMID 22642626, 2012). "Alzheimer's disease is associated with impaired clearance of β-amyloid from the brain, a process normally facilitated by ApoE." (PMID 23029362, 2012). "Frequency of the APOE-ε4 allele, the main genetic risk factor for late-onset Alzheimer's disease, was substantially higher in MCI and AD patients than controls." (PMID 22485168, 2012). "It perhaps involves in ApoE expression and has been linked to the familial onset form of Alzheimer’s disease." (PMID 23285040, 2012).
Alzheimer disease (continued). "The ApoE E4 polymorphism of the gene coding for this protein has been associated with increased risk of Alzheimer′s disease, and also of postoperative delirium." (PMID 23095517, 2012). "The apolipoprotein E (APOE) ε4 allele is the major genetic risk factor for Alzheimer's disease, but mounting evidence indicates that it also conditions cognitive function and brain integrity in humans across the lifespan." (PMID 23284783, 2012). "Analysis of ApoE alleles in Alzheimer disease and controls demonstrated that there was a highly significant association of ApoE type 4 allele (APOE-epsilon 4) and late-onset familial Alzheimer disease." (PMID 22934024, 2012). "Inheritance of the human ε4 allele of the apolipoprotein (apo) E gene (APOE) significantly increases the risk of developing Alzheimer’s disease (AD), in addition to adversely influencing clinical outcomes of other neurologic diseases." (PMID 22883744, 2012). "The three common ApoE isoforms (ApoE2, E3, and E4) each differ by a single amino acid, with ApoE4 increasing and ApoE2 decreasing the risk of Alzheimer’s disease (AD)." (PMID 22675504, 2012). "The E4 allele of the ApoE gene has consistently been shown to be related to an increased risk of Alzheimer's disease (AD)." (PMID 23152815, 2012). "Apolipoprotein E (APOE) is an important risk factor for Alzheimer's disease (AD) and is present in 30–50% of patients who develop late-onset AD." (PMID 22530123, 2012). "The apolipoprotein E epsilon 4 (APOE-4) is associated with a genetic vulnerability to Alzheimer's disease (AD) and with AD-related abnormalities in cortical rhythms." (PMID 23050006, 2012). "A2m is also known to interact with longevity-associated ApoE (apolipoprotein E) and is associated with Alzheimer's disease." (PMID 22073188, 2011). "Absence or structural mutations of apoE cause significant disorders in lipid metabolism, cardiovascular disease, and Alzheimer's disease." (PMID 21253017, 2011). "The apolipoprotein E (APOE) ε4 allele has been reported to be a risk factor for Alzheimer's disease (AD) and dementia with Lewy bodies (DLB)." (PMID 21552550, 2011). "APOE-associated Alzheimer's disease is due to a specific variation in the APOE gene called e4 allele." (PMID 22191060, 2011). "Based on replication in a large number of studies, the only firmly established genetic susceptibility factor for Alzheimer disease is the ε4 allele of ApoE." (PMID 22114744, 2011). "The APOE ε4 allele represents a major susceptibility factor for late onset Alzheimer's disease (LOAD), with carriers having approximately a threefold risk (over tenfold for homozygotes) of developing LOAD compared with noncarriers." (PMID 21215387, 2011). "The apolipoprotein E gene (APOE) coding polymorphism modifies the risks of Alzheimer's disease, type 2 diabetes, and coronary heart disease." (PMID 22028770, 2011). "ApoE ε4 carriers have an increased risk of cardiovascular disease and Alzheimer's disease, while ApoE ε2 carriers are protected from these diseases." (PMID 21418511, 2011). "Apolipoprotein E (APOE) genotype (ε2/ε3/ε4: rs429358 ε4 allele; rs7412 ε2 allele) is strongly associated with both lipid levels and Alzheimer's disease." (PMID 21215387, 2011). "Aside from the coding variants, single nucleotide polymorphism (SNP) of the APOE promoter has also been shown to modify the risk of Alzheimer's disease." (PMID 22028770, 2011). "Apolipoprotein E (apoE) and apoE/amyloid-β (Aβ) transgenic (Tg) mouse models are critical to understanding apoE-isoform effects on Alzheimer's disease risk." (PMID 22028984, 2011). "For example, the APOE promoter −491A genotype has been associated with a higher plasma level of apoE and increased risk for Alzheimer's disease as compared to its −491T counterpart." (PMID 22028770, 2011). "Apolipoprotein E (APOE), which its ε4 allele has been reported as a risk factor in late onset Alzheimer’s disease (AD), is the main cholesterol carrier in the brain." (PMID 22737475, 2011).